BDNF (brain derived neurotrophic factor)
Diseases named in the same sentence as BDNF in open-access papers (continued):
Sharing a sentence is not in itself a finding about the gene and the disease.
depression (continued). "In addition, hippocampal BDNF knockdown mice, microinjected with lentiviral vectors, showed reduced neurogenesis and depression-like behaviors." (PMID 34577589, 2021). "BDNF has become an important biomarker in the pathogenesis and treatment of depression." (PMID 34207545, 2021). "Recent rodent studies indicated that BDNF might have a role in preventing the increase in ROS found in depression most probably via a nuclear factor erythroid-derived 2-like 2 (Nrf2) dependent mechanism." (PMID 34299103, 2021). "CSS may alleviate anxiety and depression by regulating gut microbiota and NF-κB-involved BDNF expression." (PMID 34391441, 2021). "The expression level of BDNF could have been reduced in the hippocampus of stressed animals and the blood of patients with depression." (PMID 33924992, 2021). "In animal models, infusion of BDNF could reduce depression-like behavior, and increased expression of BDNF counteracts the effects of stress." (PMID 34827728, 2021). "Multivariate analyses indicated that a composite ARMS measure comprised of PQ‐B scores plus anxiety and depression symptoms revealed significant genotype differences, with lowest risk and highest resilience for allelic carriers of 5‐HTTLPR‐short and BDNF Met polymorphisms." (PMID 33932264, 2021). "Similarly, low serum BDNF levels were reported in patients with major depressive disorder; however, the levels were elevated by antidepressant treatment." (PMID 34439529, 2021). "Together, these results suggested that jasmine tea soup, especially at low doses, could effectively ameliorate the symptoms of depression induced by CUMS via an increase in BDNF, GLP-1, and 5-HT." (PMID 35010973, 2021). "Finally, facial injection of BoNT/A causes structure or function changes in the brain to alleviate depression, for example, upregulation of brain-derived neurotrophic factor (BDNF) expression in the brain." (PMID 33967844, 2021). "Interestingly, an inverse correlation between increases in BDNF and depression severity were also reported in this study." (PMID 33567631, 2021). "The neurotrophic hypothesis of depression indicates that alterations in BDNF levels occur in key limbic structures to contribute to the pathogenic processes." (PMID 33673282, 2021). "CPT relieves the depressive-like state in CUS-induced mice by enhancing neurogenesis and inhibiting inflammation through the BDNF/TrkB and NF-κB pathways and could therefore serve as a promising candidate for the treatment of depression." (PMID 34900345, 2021). "Overall, these results indicate that GSB-106 exhibits an obvious antidepressant-like effect in a mouse model of UCMS-induced depression that was mediated, at least partially, by an increase in BDNF level and site-selective phosphorylation of TrkBY706/707 and TrkBY816." (PMID 34948177, 2021). "Taken together, it is rational to deduce that taVNS could alleviate depression symptoms and sleep quality in alcohol-dependent patients after withdrawal, which might be involved in the increased levels of peripheral BDNF." (PMID 34526917, 2021). "Moreover, studies conducted on patients with depression also showed a decrease in BDNF expression (ELISA) and a higher level of miR-132 and miR-182-5p expression in the serum (real-time PCR method)." (PMID 34202956, 2021). "Interestingly, a recent study reported that serum BDNF, as well as irisin andadropin, is correlated with the occurrence of depression in coronary heart disease patients." (PMID 33477900, 2021). "Targeting of Shati/Nat8l would allow BDNF to be striatum-specifically regulated, and the striatal Shati/Nat8l-BDNF pathway could be a promising novel therapeutic agent for the treatment of depression by modulating sensitivity to stress." (PMID 34577589, 2021). "Previous research suggested that the increased serum levels of proBDNF or decreased BDNF/proBDNF ratio could be a serum marker for depression." (PMID 33673283, 2021).
depression (continued). "Additionally, H. erinaceus improves depression and anxiety-related mood disorders and nocturnal rest via modulation of brain-derived neurotrophic factor (BDNF) and its precursor pro-BDNF in serum." (PMID 33800983, 2021). "Serum BDNF concentrations were diminished in patients with depression." (PMID 33506043, 2021). "Clinically, patients with anxiety, but not depression, and those using biologics were associated with lower BDNF levels." (PMID 33673283, 2021). "Additionally, the self-rating depression scale (SDS) score was negatively correlated to serum BDNF levels but positively correlated to serum miR-132 levels." (PMID 34947970, 2021). "Several studies have indicated that ACC BDNF can be regulated in an activity-dependent manner, and its alternation may contribute to chronic pain, depression, and other mental disorders." (PMID 34526080, 2021). "Furthermore, the role of Nrf2 and BDNF in the brain regions from mice with depression-like phenotypes was examined." (PMID 33627628, 2021). "As a physiological regulator of BDNF production, ET has been revealed as an alternative strategy for the therapy and treatment of patients with disorders of nervous system, including depression." (PMID 34300001, 2021). "As 5-HT1A receptor (5-HT1AR) and brain-derived neurotrophicfactor (BDNF) are critically involved in depression and anxiety, wefurther evaluated 5-HT1A receptor functionality by [35S]GTPγS autoradiography and BDNF mRNA expression by in situ hybridization techniques." (PMID 33974408, 2021). "BDNF is involved in the pathophysiological process of depression and plays an antidepressant role." (PMID 34040537, 2021). "Postmortem studies have demonstrated that patients with depression and related mental illnesses have lower BDNF and/or TRKB mRNA levels, reduced cortical neuron size, lower synaptic protein levels, decreased mTOR signaling, and fewer dendritic spines/synapses in the PFC." (PMID 34671279, 2021). "Conditional BDNF knockout mice display increased depression-related behaviors, indicating that low expression of BDNF might precipitate depressive disorder." (PMID 34141514, 2021). "They present decreased BDNF levels, and anxiety- and depression-like behavior." (PMID 34068707, 2021). "Currently, a leading hypothesis for depression suggests that BDNF signaling pathway is intimately involved in depression pathophysiology." (PMID 34654365, 2021). "Few studies have investigated the relationship between BDNF and late-life depression." (PMID 33643008, 2021). "Given that depression and anxiety are frequent comorbidities in eating disorders including AN, decreased serum BDNF levels in AN and BN could at least be partially accredited to comorbidity." (PMID 33572701, 2021). "This study evaluates a different BDNF polymorphism and found that men with t-allele, a different polymorphism from val66met, had a higher risk for depression after six weeks, while this was not the case for women." (PMID 33808272, 2021). "The differences of NI in individuals may reflect different levels of sensitivity of depression symptoms to BDNF levels." (PMID 34776888, 2021). "Our previous work has shown that CRS could up-regulated the expression of Pdcd4 that contribute to synaptic plasticity impairment and depression-like behavior by inhibiting the expression of BDNF." (PMID 34772918, 2021). "The influence of BDNF in relation to depression has been amply studied." (PMID 34942936, 2021). "Hence, we focused on the modulation of estrogen-BDNF-mTORC1 signaling in depression and its possible mechanisms in recent years." (PMID 33628219, 2021). "In addition, treatment with antidepressants and anti-anxiety agents, as well as repetitive transcranial magnetic stimulation treatment has been shown to enhance GABA and BDNF expression in depression." (PMID 34674715, 2021). "Decreased Nrf2 expression might decrease BDNF expression in the mPFC and hippocampus, resulting in a depression-like phenotype." (PMID 33627628, 2021).
depression (continued). "Therefore, the BDNF-mTORC1 pathway can indeed regulate depression through autophagy, but its specific mechanism remains to be studied." (PMID 33628219, 2021). "We examined whether Nrf2 plays a role in LPS-induced depression-like behaviors by elevating BDNF expression and inhibiting BDNF transcriptional repressor expression." (PMID 33627628, 2021). "Finally, we discussed how to regulate BDNF dorsal striatum-specifically and the application of these findings as a novel strategy for the treatment of depression." (PMID 34577589, 2021). "In animal models of depression, chronic probiotic administration can reduce anxiety and depressive symptoms and correlates with the normalization of biological indicators of depression, such as corticosterone, noradrenaline, BDNF levels, and cytokines." (PMID 34248517, 2021). "Animal studies show that blocking Pdcd4 in depression promotes BDNF expression, indicating that Pdcd4 may be a potential anti-depression target." (PMID 33960267, 2021). "We recently showed BDNF function in the dorsal striatum of patients with depression." (PMID 34577589, 2021). "All these data show that EA can prevent depression-induced decreases in BDNF signaling." (PMID 33436036, 2021). "The acute mTOR downregulation in the IL cortex leads to reduced BDNF mRNA levels in mPFC, together with impaired 5-HT and glutamate neurotransmission in the DRN, disturbances linked to neuropathophysiology of depression, as reported in preclinical and clinical studies." (PMID 34445375, 2021). "For example, several open-label studies on ketamine and BDNF found a negative association of the increase in BDNF following a single ketamine infusion with the severity of depression." (PMID 33850645, 2021). "An interesting point for future investigation would be to verify whether raising the BDNF with RR could reduce the severity of depression in clinically depressed patients." (PMID 34220571, 2021). "These researches manifest that suppression of NAc BDNF signaling pathway could offer a novel therapeutic approach to depression." (PMID 34654365, 2021). "Also, the timing of serum BDNF level sampling and of post-stroke depression assessments should be considered carefully so that observations can be related to the acute vs. chronic stages of post-stroke recovery and symptom evolution." (PMID 34141514, 2021). "Mesolimbic BDNF function is also reportedly involved in the pathogenesis of depression." (PMID 34577589, 2021). "We proposed that the local expression and the effect of BDNF in the brain could be critical for the development of depression and anxiety." (PMID 33673283, 2021). "It has been reported that BDNF is negatively correlated with severe depression." (PMID 34567219, 2021). "Qigong has been shown to alleviate the severity of psychological symptoms (e.g., depression and anxiety) likely through modulations of the hypothalamic-pituitary-adrenal axis, monoamine neurotransmitter (e.g., serotonin), brain-derived neurotrophic factor, and adiponectin." (PMID 34567220, 2021). "BDNF plays a pivotal role in regulating a long-term synaptic plasticity in the hippocampus, and the down-regulation of BDNF levels contributes to the depression-related cognitive impairments." (PMID 33441611, 2021). "Several clinical applications of BDNF have been developed, which can treat common neuropsychiatric diseases, such as Parkinson’s disease, Alzheimer’s disease, depression, schizophrenia, and so forth, and can also be used as a reference indicator for early diagnosis and prognosis of certain tumors." (PMID 33477900, 2021). "Overexpression of miR-182 increased the symptoms of depression and decreased the BDNF levels." (PMID 34685444, 2021). "However, compared with HC, patients with depression have lower serum and plasma BDNF concentrations." (PMID 34531719, 2021). "Furthermore, increased level of cortisol inhibited BDNF, leading to neurodegeneration and partly to the development of symptoms of depression." (PMID 34064233, 2021).
depression (continued). "However, recent theories underscore the role of Brain-derived neurotrophic factor (BDNF) in the pathogenesis of depression." (PMID 34922595, 2021). "Given these broad signaling effects, it is not surprising that altered BDNF expression has also been implicated in development of neuropsychiatric disorders such as depression, obsessive-compulsive disorder, substance use disorders, and schizophrenia." (PMID 33757426, 2021). "This is consistent with the result from a study using a biphasic stress model on sleep, which reported a fast increase in serum BDNF levels as seen in patients with acute stress and, sleep deprivation, but a decrease in levels with chronic stress, sleep disturbance and depression." (PMID 34081742, 2021). "Similarly, animal models have also shown that BDNF expression in the hippocampus and cerebellum of rats was significantly lower in patients with depression post stroke compared to normal controls." (PMID 33919670, 2021). "The role of BDNF in the central nervous system (CNS) in depression may depend on the circuit and region, with both antidepressant and antidepressant effects." (PMID 34577589, 2021). "Many studies used BDNF level for clinical correlations or outcome predictions in various neurological and psychiatric diseases, such as Alzheimer disease, Parkinson disease, Huntington disease, major depressive disorder, and multiple sclerosis." (PMID 34539561, 2021). "The limitation of monoamine theory in practical treatment makes people realize that neurotrophin is indispensable to depression treatment, and accumulating evidence has supported the critical role of brain-derived neurotrophic factors (BDNF) in emotion regulation." (PMID 34772918, 2021). "Still, it is tempting to challenge BDNF as a possible target that could modify obesity, psoriasis severity, and the related depression at once." (PMID 34685457, 2021). "Likewise, elevation of IL-2 is implicated in the pathogenesis of neuropsychological conditions like depression and schizophrenia, although it is required for normal hippocampal function or BDNF signalling." (PMID 33985854, 2021). "It was proved that BDNF was involved in both depression and anxiety." (PMID 33603780, 2021). "The BDNF hypothesis of depression is justified because opposing actions of stress and antidepressant treatment are observed on existing BDNF levels in serum and limbic brain regions, such as the hippocampus." (PMID 34298958, 2021). "BDNF has also been demonstrated to possess antidepressant effects in animal models of depression." (PMID 34141514, 2021). "In addition, in rodents’ model of depression, BDNF effectively prohibited cytokines by down-regulating NF-κB signaling." (PMID 34772918, 2021). "Reduced BDNF levels may have an impact on the development of depression in patients with Parkinson’s disease." (PMID 33804468, 2021). "The depression scores in both groups were positively correlated with NP level (r = 0.29, P=0.016) and negatively correlated with levels of E (r=0.228, P=0.012), NE (r=0.400, P=0.003), and BDNF (r=0.450, P=0.000)." (PMID 34046258, 2021). "BDNF is also involved in psychiatric diseases such as schizophrenia, autism, and depression." (PMID 34577589, 2021). "Furthermore, chronic, uncontrollable stress and depression are both characterized by decreased neuroplasticity and neurogenesis, in which brain-derived neurotrophic factor (BDNF) signaling is disordered." (PMID 34177605, 2021). "Brain dysfunction, including depression, can be reflected by hippocampal and blood levels of BDNF." (PMID 33920851, 2021). "The BDNF related signaling pathway is one of the pathogenesis of depression." (PMID 34419170, 2021). "A previous study showed that p75NTR might mitigate depression and prompt BDNF maturation, which may be counterproductive for PSD." (PMID 34759285, 2021).
depression (continued). "Our findings suggest that hippocampal GPAT4 may participate in HFD induced depression through AMPK/CREB/BDNF pathway, which provides insights into a clinical target for obesity-associated depression intervention." (PMID 34054732, 2021). "Furthermore, neurotrophins, especially BDNF and NT-3, have been investigated in mood disorders and found to play a role in depression and anxiety." (PMID 34620525, 2021). "A study of the M1- and M3-AChR antagonist penehyclidine hydrochloride (PHC) also gave similar results: PHC could improve depressive-like behaviors in depression model mice and increased BDNF expression could be observed in the hippocampus." (PMID 34093254, 2021). "Therefore, BDNF has been recognized as a therapeutic factor in clinical depression, especially in response to ET." (PMID 34300001, 2021). "In conclusion, recovery from depression-like behavior after mild bTBI may be mediated by hippocampal neurogenesis induced by increased BDNF and serotonin levels as well as the inhibition of pCREB downregulation in the hippocampus." (PMID 33643190, 2021). "Moreover, increased hippocampal BDNF levels, as a result of peripheral administration, enables mice to recover from depression." (PMID 33920851, 2021). "Interestingly, the conditional overexpression of BDNF in the hippocampus also showed an antidepressant effect even in serotonin transporter knockout rats, which showed depression-like behaviors." (PMID 34577589, 2021). "First, disrupted neuroplasticity in depression with diminished level of essential trophic factors such as brain-derived neurotrophic factor (BDNF) may contribute to the death of retinal ganglion cells (RGC) in glaucoma." (PMID 33723349, 2021). "Similarly, microinfusion of BDNF into the hippocampus restored depression-like behaviors induced by chronic stress." (PMID 34577589, 2021). "Studies have shown that BDNF levels are lower in depression patients than healthy people." (PMID 34776888, 2021). "Likewise, it didn’t change (p > 0.05) the levels of pro-BDNF, serotonin and noradrenaline in the cerebral cortex of LPS-induced depression mice model." (PMID 34790666, 2021). "It indicates that not only the rapid antidepressant response is dependent on BDNF translation, but there is a possible translation relevant regulation of BDNF function in the development of depression, and rectify the dysfunction will contribute to the MDD treatment." (PMID 32203159, 2021). "Furthermore, horticulture activities been shown to reduce depression and anxiety, increase self-identify, and increase levels of brain-derived neurotrophic factor (BDNF) in older adults, leading to improved cognitive function." (PMID 34948539, 2021). "Decreased of the dorsal striatal BDNF-induced stress resilience via regulation of Shati/Nat8l may be a beneficial therapeutic strategy for depression." (PMID 34577589, 2021). "Therefore, making clear of the BDNF translational machinery in depression is important for depression therapy." (PMID 32203159, 2021). "In agreement with the neurotrophic hypothesis of depression, these animals present, under basal conditions, downregulation of BDNF mRNA (especially exon IV) and protein levels in the ventral hippocampus and prefrontal cortex." (PMID 34068707, 2021). "Other molecular markers, including brain-derived neurotrophic factor (BDNF), homocysteine, triiodothyronine, uric acid, total bilirubin and leptin have also been associated with the development of depression in stroke." (PMID 34607565, 2021). "Moreover, prevalence antidepressants such as selective serotonin reuptake inhibitors (SSRIs), selective noradrenalin reuptake inhibitors (SNRIs), ketamine, and scopolamine alleviate depression by enhancing BDNF production." (PMID 34772918, 2021). "As a key sensor of antidepressant drugs, BDNF may be a biomarker that can be used to monitor depression treatment response." (PMID 35194435, 2021).